BATF (basic leucine zipper ATF-like transcription factor)
Diseases named in the same sentence as BATF in open-access papers (continued):
Sharing a sentence is not in itself a finding about the gene and the disease.
BATF also shares sentences with these, for which no sentence is quoted: multiple myeloma (5 papers); Arthritis (2); diffuse large B-cell lymphoma (2); non-small cell lung carcinoma (2); primary effusion lymphoma (2); schizophrenia (2); scrub typhus (2); thyroid cancer (2); acute graft versus host disease (1); adult T cell leukemia (1); airway allergy (1); bipolar disorder (1); breast tumors (1); cardiac hypertrophy (1); cardiomyopathy (1); cardiovascular disease (1); coronary disease (1); diabetic nephropathy (1); graft versus host disease (1); hemorrhage (1); Hepatic steatosis (1); Hodgkins lymphoma (1); immune disease (1); infectious disease (1); inflammatory bowel disease (1); liver cancer (1); myocardial infarction (1); non-Hodgkin lymphoma (1); prostate adenocarcinoma (1); prostate carcinoma (1).
A further 5 diseases each share a sentence with BATF in 1 paper.